BRAF (B-Raf proto-oncogene, serine/threonine kinase)
Diseases named in the same sentence as BRAF in open-access papers (continued):
Sharing a sentence is not in itself a finding about the gene and the disease.
melanoma (continued). "Co-treatment with BRAF inhibitors and with inhibitors of BCL2 might overcome intrinsic resistance to BRAF inhibitors (also seen in melanoma cells in vitro and in vivo)." (PMID 26636651, 2015). "Here, we describe two cases of possible primary pulmonary malignant melanoma with wild-type BRAF and no expression of PD-L1." (PMID 26376781, 2015). "Activation of BRAF/MEK/ERK signaling promotes invasion and metastasis of melanoma cells." (PMID 26033450, 2015). "For example, unlike melanoma, BRAF inhibitor monotherapy showed limited clinical response for patients with colorectal adenocarcinoma (CRC) harboring BRAFV600E." (PMID 29061943, 2015). "The functional studies in this paper focused on BRAF, an effector of the growth factor signaling and upstream regulator of the mitogen-activated protein kinase/ERK cascade and a therapeutic target in other cancers such as melanoma." (PMID 26661278, 2015). "We were further encouraged that the probe resulted in strong fluorescence in melanoma cells regardless of BRAF wild type (WT) or mutant status, and with peak fluorescence reached by 48 hours." (PMID 25807549, 2015). "We used the syngeneic mouse model of BRAFV600E-driven melanoma SM1, which secretes CSF-1, to evaluate the ability of the CSF-1 receptor (CSF-1R) inhibitor PLX3397 to improve the antitumor efficacy of the oncogenic BRAF inhibitor vemurafenib." (PMID 25939769, 2015). "Down-regulation of STAT3, by BRAF–MEK inhibitors may decrease the activity of anti-apoptotic protein Mcl-1 and reduce melanoma cell survival." (PMID 26322273, 2015). "A previous study of cancer cells not specific to melanoma reported paradoxical activation of MEK1/2 upon MEK1/2 inhibition in a BRAF-/NRAS-wild-type setting, citing that signaling in these cells is regulated by receptor tyrosine kinases (RTKs)." (PMID 26084293, 2015). "Combined therapies that block both BRAF and PI3K/AKT signalling have therefore been suggested because it could lead to the reactivation of senescence and elimination of melanoma cells refractory to BRAF inhibition." (PMID 25595898, 2015). "Over the last few years, clinical trials with BRAF and mitogen-activated protein/extracellular signal-regulated kinase (MEK) inhibitors have shown significant clinical activity in melanoma, but only a fraction of patients respond to these therapies, and development of resistance is frequent." (PMID 24920406, 2014). "We confirmed differential vemurafenib activity in BRAF mutant (A375, SK-Mel-28) and non-mutant (SK-Mel-147) melanoma cell lines with regard to growth and pERK inhibition occurring only in BRAF mutant cells." (PMID 24980819, 2014). "For example, a recent trial showed that treatment with IL-21 produced an overall response rate of 22.5% in melanoma and responses were not related to the status of BRAF." (PMID 24743024, 2014). "Canertinib has been demonstrated to increase the anti-proliferative effects of vemurafenib in the BRAF mutant melanoma cell lines, but little or no enhanced effect was noted with the combination treatment in the wild type melanoma cell lines." (PMID 25110867, 2014). "A single report claimed that selective BRAF inhibition decreases tumor-resident lymphocyte frequencies in a genetically engineered mouse (GEM) melanoma model; moreover, treatment with ipilimumab did not restore the numbers of TIL." (PMID 24743024, 2014). "Also, FOXD3-dependent upregulation of the EGFR family member ERBB3 was described after BRAF- or MEK inhibition in melanoma cells, resulting in enhanced responsiveness to ERBB3 ligands and the sensitization towards the BRAF inhibitor PLX4720 by lapatinib." (PMID 24970815, 2014).
melanoma (continued). "BRAF inhibitors such as vemurafenib (PLX4032, RG7204) and dabrafenib (GSK2118436) cause marked responses in patients with BRAF-mutant melanoma, but not in patients with BRAF wild-type melanoma." (PMID 25422890, 2014). "It is important tostress that dabrafenib should not be used in patients with BRAF wild-type melanoma, as in vitro studieshave demonstrated a proliferative effect in nonmutated BRAF melanomas following exposure to BRAFinhibitors." (PMID 25089220, 2014). "In BRAF wild-type melanomas, we never identified a minor positive subpopulation and BRAF-mutant protein expression was homogeneous in most cases (97%), also when tumors harbored a mixed cell population." (PMID 25526463, 2014). "Whether microRNAs (miRNAs) have a role in BRAF- and NRAS-driven melanoma initiation and progression remains to be determined." (PMID 24550252, 2014). "In addition, the BRAF inhibitor, vemurafenib, has not been considered as a common treatment option for patients with mucosal melanoma, as BRAF mutations have been identified much less frequently in patients with mucosal melanoma compared with those arising from cutaneous surfaces." (PMID 25120707, 2014). "While targeting of mutant BRAF with small molecule inhibitors such as vemurafenib and dabrafenib showed promising results in BRAF mutant melanoma, there are no therapeutics available which specifically inhibit mutant NRAS." (PMID 25277205, 2014). "Besides the expected coding mutations in BRAF, NRAS, CDKN2A, and other genes detected, significant numbers of recurrent copy number variants and structural rearrangements found in this analysis of 13 WGS cases suggest that they may be important initiating and metastatic events in melanoma." (PMID 25393105, 2014). "Preclinical studies have demonstrated that BRAF plays an important role in regulating the mitogen-activated protein kinases (MAPK) signaling cascade by promoting proliferation, survival, and invasion of melanoma cells." (PMID 24466036, 2014). "Two mutant and two non-mutant BRAF melanoma cell lines were subjected to Usp5 KD and their growth kinetics were assessed over four days after plating equal numbers of initiating cells." (PMID 24980819, 2014). "While there is no efficient targeted therapy against wild type BRAF melanomas, BRAF mutant (mutBRAF) melanomas are addicted to the MAPK-pathway and small molecule inhibitors targeting either mutBRAF or MEK have shown impressive clinical responses." (PMID 24941944, 2014). "The role of SOX10 in regulating EGFR in melanoma was further supported by the discovery of an inverse relationship between SOX10 and EGFR gene expression in a panel of BRAF mutant melanoma cell lines, as well as in a few BRAF mutant melanoma patient samples following treatment-associated resistance." (PMID 25031620, 2014). "The present study also shows that somatic activating BRAF, RAS, GNAQ, GNA11 and KIT mutations, frequently observed in human melanomas, are not required for melanoma development in Grey horses." (PMID 25413220, 2014). "PTEN-negative or AKT3-overexpressing melanomas do not undergo apoptosis in response to BRAF inhibition and do not upregulate pro-apoptotic protein BIM." (PMID 24743024, 2014). "The interval between the diagnosis of the initial melanoma to regional nodal metastasis was not significantly different between the BRAF-mutant and -WT patients (median, 10 months; P=0.29) or between NRAS-mutant and -WT patients (median, 10 months; P=0.34)." (PMID 24959217, 2014). "While Wnt/β-catenin signaling has not been the focus of existing therapeutic efforts in melanoma, there is accumulating evidence that signaling cross-talk between this pathway and BRAF/MAPK signaling influences melanoma progression." (PMID 24733413, 2014). "In the case of vemurafenib, <80% pathway inhibition in BRAF (V600E) mutant melanoma afforded no tumor shrinkage, while >90% inhibition showed profound clinical benefit." (PMID 25531068, 2014).
melanoma (continued). "Furthermore, inhibition of BRAF with vemurafenib, or MEK with UO126, potentiated effects of Nutlin3 and cyclin B /CDK1 inhibition, inducing apoptosis of melanoma in vitro and in vivo." (PMID 24743024, 2014). "From the pathogenetic point of view, the mitogen-activated protein kinase (MAPK) signal transduction pathway (including the cascade of NRAS, BRAF, MEK1/2, and ERK1/2 proteins) has been reported to play a major role in both the development and progression of melanoma." (PMID 24885594, 2014). "In support, the Noxa protein levels in BRAFV600E melanoma cells treated with PLX4720 in the presence of the proteasome inhibitor MG132 remained significantly lower compared to those without exposure to the BRAF inhibitor." (PMID 25365078, 2014). "The interval between the diagnosis of the initial melanoma to regional nodal metastasis (median, 10 months) was not significantly different between BRAF-mutant and -WT patients." (PMID 24959217, 2014). "GDC-0980 was reported to be a potent inhibitor of breast, prostate and lung cancer cell growth and was much less effective against melanoma and pancreatic cancers, most likely due to the presence of highly active KRAS and BRAF usually encountered in these cancers." (PMID 25221930, 2014). "Currently, there is no effective targeted therapy for BRAF wild-type melanoma, which comprises 50% of all melanomas." (PMID 25142146, 2014). "Interestingly, the BRAF and MEK inhibitor combination (GSK2118436 and GSK1120212) demonstrated a potential reduction in drug resistance in melanoma." (PMID 25361007, 2014). "Toxicity from TKI or mTOR inhibitors for RCC and from chemotherapy, BRAF inhibitors or anti-CTLA-4 antibodies for melanoma are low-grade but continuous and exert a negative impact on quality of life." (PMID 25245327, 2014). "Both the non-competitive inhibitory properties of SCH772984 and its ability to cause reactivation of the MAPK pathway may explain the synergy seen with combination BRAF- and ERK-inhibition in the vast majority of BRAF-mutant melanoma." (PMID 25142146, 2014). "Because BRAF and ERK2 are the main components of MAPK signaling, the overexpression of miR-524-5p effectively inhibits MAPK/ERK signaling, tumor proliferation, and melanoma cell migration." (PMID 25275294, 2014). "Additionally, inhibition with BRAF and MEK inhibitors increased the recognition of these melanoma antigens by antigen-specific T lymphocytes." (PMID 25610709, 2014). "Recent publications on combined therapy with BRAF and MEK inhibitors (dabrafenib and trametinib respectively) highlighted significant increases in progression-free survival, suggesting the importance of these pathways in melanoma biology." (PMID 25057921, 2014). "Furthermore, a growing body of evidence supports that BRAF-MEK-ERK (MAPK) and NFκB pathways play an important role in invasion and metastasis since they are constitutively activated in melanoma." (PMID 24466036, 2014). "The BH3 mimetic ABT-737 (inhibiting both Bcl2 and Bcl-xL) sensitizes human melanoma cells to apoptosis induced by selective BRAF inhibitors, but does not reverse acquired resistance in vitro." (PMID 24743024, 2014). "Our results suggest that combining clinically approved γ–secretase inhibitors, which block Notch activation, with BRAF inhibitors, which block BRAF-MEK-ERK signaling, might be a more effective treatment of BRAF/NRAS mutant melanomas." (PMID 24550252, 2014). "In a recent study, mutant BRAF-selective inhibitor and anti-CTLA-4 mAb were used in combination to treat transgenic mice with mutant BRAF and PTEN deletion that spontaneously developed melanoma." (PMID 23755373, 2013). "We observed that there was no apparent correlation between dinaciclib response and BRAF/NRAS mutational status, leading us to conclude that dinaciclib had broad-spectrum anti-melanoma activity and was not conclusively mutation specific." (PMID 23527225, 2013).
melanoma (continued). "Resistance to BRAF inhibitors develops relatively rapidly because of BRAF-independent activation of MEK and ERK and other chemotherapeutic approaches will be necessary, both for melanomas lacking mutant BRAF and for melanomas that have developed resistance." (PMID 23658559, 2013). "Despite substantial recent advancements in melanoma therapy with T-cell antibodies such as anti-CTLA4 and anti-PD1, or with targeted therapies such as BRAF or MEK inhibitors, adoptive cell therapy with tumor infiltrating lymphocytes still offers the most robust clinical cure rates." (PMID 23483943, 2013). "Expression levels of full-length BRAF mRNA was significantly higher in the malignant melanoma samples as compared to non-malignant nevi (p = 0.007)." (PMID 23673558, 2013). "By contrast, the killing of mutant BRAF melanoma cells by Zelboraf works very well in the absence of any obvious direct source of ROS." (PMID 23303309, 2013). "It has marked antitumor effects against melanoma cell lines with the BRAFV600E, mutation but not against cells with wild-type BRAF." (PMID 23340652, 2013). "In sum we show that the presence of a BRAF- or NRAS mutation, at least in the present series, is not biologically relevant in the development of melanomas that arise in association with a nevus." (PMID 23861977, 2013). "Our results do not support the concept that oncogenic BRAF or NRAS mutations play a major role in the development of melanoma from nevi and do not support the multistep theory of melanoma progression in its current form." (PMID 23861977, 2013). "This metabolic phenotype, which is present irrespective of the expression of PGC1α, renders BRAF inhibitor–resistant melanoma cells highly vulnerable to several mitochondrial-targeted compounds including the mitochondrial pro-oxidative drug, elesclomol." (PMID 24161908, 2013). "The results of this study show that dabrafenib is well tolerated and can represent a valid therapeutic strategy in patients with BRAF-mutant melanoma with BM either previously treated or not." (PMID 23340652, 2013). "In conclusion, we have assessed the responses of a series of 44 melanoma lines, generally of low passage number, to CI-1040, a prototypic MEK inhibitor, as well as to trametinib, a clinical MEK inhibitor and vemurafenib, a clinical BRAF inhibitor." (PMID 23658559, 2013). "In short-term (48–72 h) in vitro experiments using BRAF mutant melanoma cell lines, apoptosis or necrosis does not have a significant role in mediating the effects of melanoma MAPK pathway inhibition on DCs." (PMID 24194739, 2013). "Regardless, the ability to bypass canonical cell death pathways to kill melanoma cells by combinations of HDAC and BRAF inhibitors may be of therapeutic advantage." (PMID 23744355, 2013). "The effects of Raf-1 on the prevention of apoptosis were demonstrated in the D594G/G469E but not BRAF V600E mutant melanoma cells by shRNA knock down of Raf-1." (PMID 23085539, 2012). "Furthermore, higher doses of inhibitor were required to limit tumour progression in BRAF wildtype and also NRAS mutant melanoma xenografts." (PMID 23039341, 2012). "Such novel approaches are urgently needed as it is clear that melanoma cells possess multiple mechanisms to bypass, or overcome drug resistance to agents with clinical success such as PLX4032 (Vemurafenib), a drug targeting mutant BRAF." (PMID 22277029, 2012). "Other BRAF inhibitors such as GDC0879 and GSK2118436/dabrafenib are currently in the development and testing phase to determine their efficacy in melanoma treatment." (PMID 23372575, 2012). "This suggests that oncogenic BRAF signaling does not decrease SLUG expression in BRAFV600E melanoma cells." (PMID 22911700, 2012). "As expected, we found the known melanoma drivers NRAS and BRAF to have the largest numbers of non-synonymous mutations in our candidate list." (PMID 22912864, 2012).
melanoma (continued). "Selective reliance on BRAF activity by cancer, but not the normal cells, makes BRAF inhibitors relatively safe and efficient against a subset of melanomas, which are hardly amenable to conventional chemotherapy." (PMID 22869096, 2012). "Inhibition of this kinase is postulated as an interesting target in BRAF mutant melanoma, but not in NRAS." (PMID 22216021, 2012). "Interestingly, subanalysis of results from phase II trials in melanoma have hinted at a greater efficacy of MEK1/2 inhibition in BRAF-mutant patients albeit in small patient numbers (15 and 67 BRAF mutant patients)." (PMID 23039341, 2012). "PTEN protein was present in 20 of the melanoma cell lines tested with a lack of the tumour suppressor being suggestive of resistance to E6201 in not only BRAF/RAS mutant lines (p = 0.12) but also if all lines are considered (p = 0.14)." (PMID 23039341, 2012). "The absence of BRAF and NRAS mutations in melanoma cell lines is associated with a greater sensitivity to dasatinib in vitro." (PMID 22127285, 2012). "Numerous recent reports focusing on BRAF-targeted therapy designed to interrupt the RAF/MEK/ERK mitogen activated protein kinase (MAPK) pathway in melanoma patients have not made any distinctions between ERK1 and ERK2." (PMID 22277029, 2012). "However, a phase I trial of the BRAF inhibitor, vemurafenib (PLX4032), showed >80% response rate in BRAF V600E positive melanoma." (PMID 26316937, 2012). "BRAF and NRAS mutations are absent in melanomas arising in the uveal layer of the eye, but mutually exclusive somatic mutations in the heterotrimeric G protein alpha-subunit, GNAQ, or in GNA11, are present in the great majority of uveal melanomas." (PMID 22515704, 2012). "This argues for a regulatory role of Spry and Spred proteins in melanoma aggressiveness independent of oncogenic BRAF-driven ERK hyperactivation." (PMID 22535842, 2012). "Regardless, MEK inhibitors have emerged as an effective strategy to target drug resistant BRAFV600E melanomas in patients with or without previous exposure to BRAF inhibitors." (PMID 23372575, 2012). "In one study of melanomas arising at chronic sun damaged sites CDK4 and CCND1 were implicated as independent oncogenes in melanomas without mutations in BRAF or N-RAS." (PMID 25562798, 2012). "Taken together, these data and the analysis of the primary tumors suggest that many primary melanomas are heterogeneous with respect to the BRAFV600E mutation, and that some of the metastasizing tumor subclones do not require the presence of the BRAF mutation." (PMID 22235286, 2012). "Treatment-induced pAKT elevation is found in BRAF wild type melanoma cells but not in a subset of melanoma cell lines harboring BRAFV600E." (PMID 22880048, 2012). "PLX-4720 arrests mutant but not WT BRAF melanoma cells at the G0/G1 cell-cycle stage and initiates apoptosis in these cells." (PMID 23085539, 2012). "Recent studies could show a positive regulatory role for BRAF-V600E in melanoma cell autophagy and enhanced LC3 lipid conjugation in the presence of hyper activated BRAF." (PMID 21853067, 2011). "It is believed that BRAF and NRAS mutations can coexist within the same melanoma but not at the single-cell level." (PMID 22039425, 2011). "In this manuscript we tested the hypothesis that combination of BRAF oncogene inhibition and metabolic modulation of AMPK would be more effective than either manipulation alone in arresting melanoma cell proliferation." (PMID 21609436, 2011). "Conversely, melanoma cell movement in the absence of BRAF inhibition was unaffected by RND3 expression or RHOA depletion." (PMID 21917148, 2011). "Approximately 20% of patients with mutant BRAF melanoma show no response, and most patients relapse, with a median PFS of 8–9 months." (PMID 21139585, 2011). "The current study identifies novel roles for RND3 and RHOA in the movement but not growth or survival of melanoma cells treated with BRAF inhibitors." (PMID 21917148, 2011).